SIRT1 (sirtuin 1)
Diseases named in the same sentence as SIRT1 in open-access papers (continued):
Sharing a sentence is not in itself a finding about the gene and the disease.
periodontitis (25 papers, 2018 to 2026). An acute or chronic inflammatory process that affects the tissues that surround and support the teeth. "Salivary SIRT-1 concentrations < 1.2 ng/mL were associated independently with periodontitis (OR = 2.84; 95% CI = 1.075-7.506; p = 0.04) in the regression analysis." (PMID 41753173, 2026). "The aim of our study was to examine the links connecting SIRT1 single-gene nucleotide polymorphisms (rs3818292, rs3758391, and rs7895833) and SIRT1 serum levels in patients with periodontitis in the Caucasian population." (PMID 35630070, 2022). "The genotypes and allele distributions of SIRT1 rs3818292 and rs7895833 were statistically significantly different between the periodontitis group and the control group of patients older than 60 years." (PMID 35630070, 2022). "The genotypes and allele distributions of SIRT1 rs3818292 and rs7895833 were statistically significantly different between the periodontitis and the control group." (PMID 35630070, 2022). "The genotype and allele distributions of SIRT1 rs3818292 and rs7895833 were statistically significantly different between the periodontitis and control groups when distinguished between gender." (PMID 35630070, 2022). "The aim of our study was to investigate the associations amid SIRT1 single-gene nucleotide polymorphisms (rs3818292, rs3758391, and rs7895833) and SIRT1 serum levels for patients affected by periodontitis in the Caucasian population." (PMID 35630070, 2022). "The SIRT1 rs7895833 AG genotype was associated with 2-fold increased odds of periodontitis under the codominant and overdominant models (OR = 1.999; CI = 1.177–3.397; p = 0.01 and OR = 1.955; CI = 1.154–3.311; p = 0.013, respectively)." (PMID 35630070, 2022). "Conclusions: in our study, the genotypes and alleles of SIRT1 rs3818292, rs3758391, and rs7895833 statistically significantly differed between the periodontitis and control groups, exclusively in the male population and subjects older than 60 years." (PMID 35630070, 2022). "The SIRT1 rs7895833 AG genotype was associated with 1.7-fold increased odds of periodontitis development under the codominant and overdominant models (OR = 1.686; CI = 1.172–2.427; p = 0.005; and OR = 1.675; CI = 1.165–2.408; p = 0.005, respectively)." (PMID 35630070, 2022). "The SIRT1 rs7895833 AG + GG genotypes were also associated with 2-fold increased odds of developing periodontitis under the dominant model (OR = 2.022; CI = 1.201–3.401; p = 0.008)." (PMID 35630070, 2022). "We found that low salivary SIRT-1 concentrations could be associated with the presence of periodontitis." (PMID 41753173, 2026). "The analysis revealed that the SIRT1 rs3818292 AG genotype was associated with 2.4-fold increased odds of periodontitis development under the codominant and overdominant models (OR = 2.367; CI = 1.238–4.525; p = 0.009 and OR = 2.378; CI = 1.244–4.545; p = 0.009, respectively)." (PMID 35630070, 2022). "However, a limited number of studies show the association between elevated serum SIRT1 and periodontitis." (PMID 35630070, 2022). "The analysis revealed that the SIRT1 rs3818292 AG genotype was associated with 2-fold and 1.9-fold increased odds of periodontitis development under the codominant and overdominant models (OR = 1.959; CI = 1.239–3.098; p = 0.004; and OR = 1.944; CI = 1.230–3.073; p = 0.004, respectively)." (PMID 35630070, 2022). "In addition, the analysis revealed that the SIRT1 rs3818292 G allele was more frequent in the female periodontitis group than in the control group (9.5% vs. 5.4%, p = 0.001)." (PMID 35630070, 2022). "The SIRT1 rs7895833 AG genotype was associated with a 1.8-fold increase in the odds of periodontitis development in the codominant model and a 1.7-fold increase in the overdominant model (OR = 1.753; CI = 1.154–2.661; p = 0.008; and OR = 1.724; CI = 1.138–2.614; p = 0.01, respectively)." (PMID 35630070, 2022).
periodontitis (continued). "Salivary SIRT-1 concentrations in periodontitis patients have been scarcely studied and only in studies with small sample sizes (the highest with 83 subjects)." (PMID 41753173, 2026). "The salivary SIRT-1 concentration showed an area under curve of 74% (95% CI = 66-86%; p < 0.001) for periodontitis diagnosis in the ROC analysis." (PMID 41753173, 2026). "In conclusion, SIRT1 is a promising therapeutic target for treating periodontitis by mitigating OS, reducing inflammatory responses, and restoring mitochondrial function." (PMID 41298339, 2025). "In fact, resveratrol administration to rats with periodontitis relieved alveolar bone resorption and activated the sirtuin 1 (SIRT1)/AMP-activated protein kinase (AMPK) and the NRF2 pathways in inflamed gingival tissues." (PMID 39456522, 2024). "In a study related to periodontitis, SIRT1 was reported to alleviate LPS-induced inflammation of human periodontal ligament fibroblasts (HPDLFs) through the downregulation of Toll-like receptor 4 (TLR 4)." (PMID 38790655, 2024). "Through the Ampk/Sirt1/Nf-κb pathway, glycolytic reprogramming triggers macrophage pyroptosis in periodontitis lesions, intensifying inflammation and bone degradation." (PMID 38892077, 2024). "The SIRT1 rs7895833 AA genotype was less frequent in the periodontitis group than in the control group (66.2% vs. 76.6%, p = 0.005), while AG was more frequent in the periodontitis group than in the control group (32.3% vs. 22.2% p = 0.005)." (PMID 35630070, 2022). "An evaluation of serum SIRT1 levels was performed in seven periodontitis-affected patients and five control group subjects." (PMID 35630070, 2022). "Current studies have proposed that resveratrol can attenuate experimental periodontitis, at least partially via activating SIRT1." (PMID 36060706, 2022). "Periodontal ligament stem cells (PDLSC) derived EVs contain miR-155-5p, which regulates the balance between Th17 and Tregs by targeting sirtuin-1 in periodontitis." (PMID 36524049, 2022). "Exosomal microRNA-155-5p from PDLSCs directly rectified the imbalance in the Th17/Treg ratio by regulating the expression of sirtuin-1 (SIRT1) in a chronic periodontitis experimental model." (PMID 33670202, 2021). "Another study found that administering resveratrol to rats suffering from periodontitis not only alleviated alveolar bone resorption but also activated vital pathways, including sirtuin 1 (SIRT1)/AMP-activated protein kinase (AMPK) and Nrf2, within inflamed gingival tissues." (PMID 40710159, 2025). "In addition to the antioxidant effect, we confirmed that HKT has an important inflammation-alleviating effect and osteogenic induction-promoting effect in improving periodontitis through the SIRT1/NOX4 pathway." (PMID 38790655, 2024). "miR-155 enhances Treg cell but inhibits Th17 cell by targeting SIRT1 in chronic periodontitis." (PMID 38264670, 2023). "Additionally, the SPMs resolvin E1 and lipoxin A4 have been reported to inhibit NF-κB activation via sirtuins (Sirt1, Sirt6, and Sirt7) in pulpitis, supporting the therapeutic potential of a Sirt6 activator in periodontitis." (PMID 37445896, 2023). "Thus, elimination of senescent PDL cells or suppression of the miR-34a-dependent SIRT1-NF-κB axis represents an attractive therapeutic strategy to prevent periodontitis in elderly people." (PMID 36863315, 2023). "The anti-oxidative stress effects of SIRT1 in periodontitis have been clearly defined." (PMID 36060706, 2022). "The analysis showed that the SIRT1 rs3818292 AA genotype was less frequent in the periodontitis group than in the control group (78.1% vs. 89.4%, p = 0.001), while the AG genotype was more frequent in patients over 60 years old than in the control group (20.5% vs. 10.6%, p = 0.003)." (PMID 35630070, 2022).
periodontitis (continued). "The genotype of SIRT1 rs7895833 AA was less frequent in the periodontitis group than in the control group (64.2% vs. 76.1%, p = 0.006), while the genotype AG was more frequent in the periodontitis group than in the control group (33.8% vs. 22.8% p = 0.001)." (PMID 35630070, 2022). "The analysis revealed that the SIRT1 rs3818292 AA genotype was less frequent in the male periodontitis group than in the control group (77.6% vs. 88.8%, p = 0.010), while the AG genotype was more frequent in the periodontitis group than in the control group (22.4% vs. 10.8%, p = 0.008)." (PMID 35630070, 2022). "Also, the SIRT1 activator resveratrol has been shown to alleviate the development of experimental periodontitis." (PMID 36060706, 2022). "The analysis showed that the SIRT1 rs3818292 AA genotype was less frequent in the periodontitis group than in the control group (80.6% vs. 89.2%, p = 0.002), while the AG genotype was more frequent in the periodontitis group than in the control group (18.4% vs. 10.4%, p = 0.004)." (PMID 35630070, 2022). "However, the therapeutic effects of resveratrol on periodontitis are mediated through multiple targets, and whether specific activation of SIRT1 can improve periodontitis still remains to be further studied." (PMID 36060706, 2022). "In addition, the SIRT1 rs7895833 AA genotype was less frequent in the periodontitis group than in the control group (60.0% vs. 75.2%, p = 0.007), while the AG genotype was more frequent in the periodontitis group than in the control group (37.6% vs. 23.6% p = 0.012)." (PMID 35630070, 2022). "Material and Methods: In this cross-sectional study, salivary SIRT-1 concentrations were measured in subjects with and without periodontitis." (PMID 41753173, 2026). "In particular, SIRT1/NOX4 regulation is considered important in regulating oxidative stress in periodontitis, based on the fact that the interaction between NOX4 and the redox system is important for ROS formation that accelerates periodontitis." (PMID 38790655, 2024). "The serum SIRT1 levels were not statistically significantly different between subjects in the periodontitis and control groups (0.984 (5.159) ng/mL vs. 0.514 (7.705) ng/mL, p = 0.792)." (PMID 35630070, 2022). "Serum SIRT1 levels were not statistically significantly different between subjects in the periodontitis and control groups." (PMID 35630070, 2022). "We found that SIRT1 serum levels were not statistically significantly different between the periodontitis patients and control group subjects (0.984 (5159) ng/mL vs. 0.514 (7705) ng/mL, p = 0.792)." (PMID 35630070, 2022). "Though there are currently no direct studies linking FOXO to the NLRP3 inflammasome in periodontitis, research has shown that SIRT1 activation by SRT1720 promotes FOXO1 deacetylation, reduces ROS overproduction, and inhibits NLRP3 inflammasome activation in models of subarachnoid hemorrhage (SAH)." (PMID 41298339, 2025). "SIRT1 and SIRT6 might be of particular importance in relation to periodontitis." (PMID 38474862, 2024).
cholestasis (24 papers, 2017 to 2025). Impairment of the bile flow caused by obstruction within the liver, or outside the liver in the bile duct system. "Overall, we here describe that during cholestasis SIRT1 is upregulated and its overexpression associates with increased liver inflammation and inflammasome activation in macrophages after BDL." (PMID 34952202, 2022). "In line with the described cross‐talk regulation, we found that SIRT1 overexpression associates with decreased FXR protein expression during cholestasis." (PMID 30229970, 2019). "Sirtuin 1, a multifaceted histone deacetylase, is upregulated in the liver macrophages of bile duct ligation mice and overexpression of which can cause the inflammation in cholestasis." (PMID 37171337, 2023). "The deficiency of intestinal SIRT1 exacerbates TNFα-mediated renal damage in mice with cholestasis." (PMID 33513830, 2021). "The level of Sirt1 mRNA level was increased in liver tissue of PBC patients, while SIRT1 protein level was up-regulated in the liver during human and murine cholestasis." (PMID 37325634, 2023). "In a similar ANIT-induced cholestasis rat model, GA activated Sirt1, which regulates bile acid metabolism through deacetylation." (PMID 36012159, 2022). "Ultimately, we demonstrate that the overexpression of SIRT1 in macrophages contributes to the aggravation of cholestasis-mediated liver injury by promoting inflammation and fibrosis." (PMID 34952202, 2022). "Here, we further define the role of SIRT1 in regulating macrophage activation during cholestasis and in response to endotoxin." (PMID 34952202, 2022). "We have used mice overexpressing SIRT1, which we treated with intraperitoneal lipopolysaccharides or induced cholestasis by bile duct ligation." (PMID 34952202, 2022). "SRT1720, a Sirt1 agonist, has been demonstrated to protect against cholestasis induced by ANIT in mice, which was partly through FXR and Nrf2 activations." (PMID 34630081, 2021). "One of the interesting findings from the previous study was the significant reduction of SIRT1 in human and mouse cholestasis." (PMID 34512782, 2021). "This demonstrates that FXR acetylation is reduced during cholestasis due to increased SIRT1 expression, which leads to increased FXR target gene expression, as is predicted to ameliorate the cholestasic phenotype." (PMID 34646233, 2021). "These divergent findings suggest that SIRT1 exerts other regulatory mechanisms which play an important role in the development of cholestasis, which warrants further investigation." (PMID 34899349, 2021). "This was consistent with previous research results that bile duct ligated models of cholestasis demonstrate decreased another sirtuin family member Sirt1 protein expression in liver." (PMID 32206298, 2020). "Formononetin can improve cholestasis through Sirt1-FXR signal pathway and alleviate liver inflammation through JNK inflammatory signal pathway." (PMID 32765278, 2020). "To gain further insight into the biological relevance of SIRT1 regulation during cholestasis, we performed BDL and fed SIRT1‐overexpressing mice with a 0.1% DDC diet that showed exacerbated parenchymal liver injury when compared to WT animals." (PMID 30229970, 2019). "Taken together, our results support the importance of preserving the fine‐tuning of SIRT1 expression to protect the liver from cholestasis‐induced parenchymal injury." (PMID 30229970, 2019). "The increase in serum markers of liver function and the profuse presence of necrotic areas observed in SIRToe mice evidenced the detrimental impact of SIRT1 overexpression during cholestasis." (PMID 30229970, 2019). "Although further work investigating in vivo activation of AMPK during cholestasis is required, our in vitro studies point to a role for AMPK in regulating SIRT1 and detrimental activity during cholestasis." (PMID 30229970, 2019).
cholestasis (continued). "Overall, our results indicate that SIRT1 expression increases during cholestasis, likely driven by accumulation of bile acids, contributing to hepatocyte cell death." (PMID 30229970, 2019). "Overall, our results demonstrate that SIRT1 overexpression contributes to the accumulation of bile acids in the liver during cholestasis upon attenuation of FXR‐mediated inhibition of bile acid synthesis." (PMID 30229970, 2019). "Overall, our results suggest that SIRT1 overexpression aggravates liver injury, hepatocellular death, inflammation, and consequent fibrogenesis in the context of cholestasis." (PMID 30229970, 2019). "In accord, in this study, we suggest that SIRT1 is up‐regulated in the liver during human cholestasis in PSC and PBC patients and in two murine models of cholestasis; after bile duct ligation (BDL) and in Mdr2 knockout mice (Mdr2–/–) mice." (PMID 30229970, 2019). "We propose that during cholestasis, the metabolic challenge involving lower nutrient/energy availability, in addition to the increase bile acid load, contribute to up‐regulation of SIRT1 and subsequent liver damage." (PMID 30229970, 2019). "Our results show that NorUDCA significantly reduced SIRT1 expression in SIRToe mice during cholestasis after BDL, both at the gene transcript and protein level." (PMID 30229970, 2019). "In this study, we suggest that SIRT1 is up‐regulated in the liver during human and murine cholestasis, and that it actively contributes to liver damage in this disease context." (PMID 30229970, 2019). "Our results indicate that SIRT1 overexpression contributes to aggravation of liver damage during cholestasis, pointing to modulation of SIRT1 as a therapeutic approach." (PMID 30229970, 2019). "Overall, our results in this alternative model of cholestasis support the detrimental impact that SIRT1 overexpression has on liver damage during cholestasis." (PMID 30229970, 2019). "We determined SIRT1 expression in livers from patients with cholestatic disease, in two experimental models of cholestasis, as well as in human and murine liver cells in response to bile acid loading." (PMID 30229970, 2019). "SRT1720 is a kind of activator of SIRT1 which is 1000 times more potent than resveratrol, and this paper is aimed to study its protective influence on hepatotoxicity and cholestasis induced by alpha-naphthylisothiocyanate (ANIT) in mice." (PMID 28553227, 2017). "SIRT1 activation prevented alcohol-, cholestasis-, and concanavalin A-induced liver injury." (PMID 33328983, 2020). "Sirt1 activation by SRT1720 is protective in mice with cholestasis induced by cholic acid feeding." (PMID 32701506, 2020). "The detrimental effects of SIRT1 during cholestasis were validated in vivo and in vitro." (PMID 30229970, 2019). "The detrimental impact of SIRT1 overexpression during cholestasis was further confirmed in an additional experimental model where 0.1% DDC–fed SIRToe mice showed increased alkaline phosphatase (AP) serum levels and wider areas of liver necrosis after 1 week of treatment." (PMID 30229970, 2019). "Next, we aimed to investigate how hepatocyte‐specific SIRT1 depletion may impact on liver injury during BDL‐induced cholestasis." (PMID 30229970, 2019). "Overall, our results suggest that SIRT1‐hepatocyte depletion exerts a degree of protection against bile‐acid–induced apoptosis, but not necrosis, explaining the transient benefits observed during cholestasis in vivo in SIRThep–/– mice." (PMID 30229970, 2019). "And it suggested that activators of SIRT1 are effective agents for the treatment of cholestasis." (PMID 28553227, 2017). "To determine whether bile acids have a direct effect on triggering SIRT1 up‐regulation during cholestasis, we exposed THLE‐2 cells (liver epithelial cells of human origin) to different bile acids, including primary and secondary species, and found a significant increase in SIRT1 expression." (PMID 30229970, 2019).